CD44 (CD44 molecule (IN blood group))
Diseases named in the same sentence as CD44 in open-access papers (continued):
Sharing a sentence is not in itself a finding about the gene and the disease.
tumor (continued). "Although cancer cell-derived factors leading to astrocytic NLRP3 inflammasome activation have not been identified, several molecules might be responsible for this phenomenon, including released TGF-β, soluble CD44, extracellular mitochondrial DNA or ATP from dying tumor cells." (PMID 37749707, 2023). "Surprisingly, 1,25(OH)2D treatment decreased CD44 nuclear localization, indicating that 1,25(OH)2D may inhibit the proteolytic processing of CD44’s intracellular cytoplasmic carboxy-terminal domain in order to limit tumor progression and metastasis via alternative genomic interactions." (PMID 37228489, 2023). "Notably, CD44 can undergo isoform switching in tumor cells to support specific cellular functions." (PMID 37958796, 2023). "CD44 + cells were associated with patients who were female (p<0.0001), aged 60 years or more (p<0.0001), white skin (p<0.0001), did not smoke (p<0.0001) or consume alcohol (p<0.0001), and had tumor sizes T1/T2 (p<0.0001)." (PMID 38126564, 2023). "It was revealed that cancers from different systems shared similar contributions of CSCs in tumour post-treatment recurrences, including the evidence of upregulated CSC markers, such as CD133 and CD44 variants in recurrent tissues, which might act as predictive, prognostic, and therapeutic targets." (PMID 37370764, 2023). "Thus, CD44 levels are a tumor marker in AL that indicates the clinical status, and its measurement may help monitor its development." (PMID 37627214, 2023). "The expression of CD44 could be associated with tumor subtypes and be a biomarker of cancer stem cells, nonetheless, it is impossible to target CD44 directly for cancer therapy since CD44 is also required for the function of stem cells as well as immune cells." (PMID 37000153, 2023). "However, the targeting capacity of HA may not be significantly impacted by hyaluronidase degradation, as CD44-mediated internalization occurs quickly when the HA or hybrids bind with tumor cells." (PMID 37376161, 2023). "Moreover, higher accumulation was seen near the tumor site, which might be explained by the interaction of HA with the hyaluronate receptor (CD44)." (PMID 38258077, 2023). "Here, a reduced CD44 expression led to significantly less adhesion (32% less adhesion) to brain endothelial cells compared to the control cells, with a relative number of adherent tumor cells (shCD44) to the brain endothelium similar to those of the HYAL1 KO cells." (PMID 36291142, 2022). "Moreover, in an in vivo experiment, tumor growth derived from CD44+ PDAC was suppressed." (PMID 35276978, 2022). "MEK/Erk and PI3K/Akt could also be activated by different growth factors, such as EGFR and ErbB3, thus tumor types and stages, as well as CD44 isoforms and expression levels should be considered when these inhibitors are combined with chemotherapy for PDAC treatment." (PMID 35931675, 2022). "Therefore, the targeted removal or inactivation of CD44 and Treg cells in the animal models might improve the immune surveillance in the tumor and enhance anti‐tumor immunity." (PMID 35522104, 2022). "Besides, tumor-associated glycoforms of conventional antigens, including SLAMF7, CLEC14A, PDPN, PODXL, and CD44, could also be ideal target antigens." (PMID 36261831, 2022). "Put together, all the evidence collected from the literature support our hypothesis that SIRT1 is a novel downstream transcriptional target of CD44/HA regulating pro-metastatic signalling pathways that are involved in tumour proliferation, migration, and invasion." (PMID 36505828, 2022). "Targeted therapy of TM4SF5 or TM4SF5/CD44 interaction may effectively inhibit tumor progression." (PMID 35936713, 2022). "Among the immune checkpoints, CD44 could promote cell-cell and cell-matrix interactions, proliferation, differentiation, invasion, and migration and is a cell adhesion receptor mainly expressed in tumors and tumor stem cells." (PMID 36268283, 2022).
tumor (continued). "Moreover, virus-mediated overexpression of miR-199 and miR-34a has been found to lead to control of tumor growth by targeting mTOR, c-MET, HIF-1α, and CD44, as well as complete tumor regression by targeting Bcl-2 and SIRT1 in xenograft murine models of HCC, respectively." (PMID 35954176, 2022). "Therefore,CD44 is not only frequently overexpressed in a range of common cancers,but it is most highly expressed within the subpopulation of cancercells within each tumor that is it most critical to target." (PMID 35938983, 2022). "It was found that surface GRP78 could promote tumor initiation in CD44+ cells." (PMID 36359223, 2022). "Several studies have demonstrated that CD44 could inhibit miR-139-5p expression in tumor cells." (PMID 35350177, 2022). "Along these lines, the cluster of differentiation 44 (CD44) antigen is a cell-surface glycoprotein receptor that can modulate several biological functions, including hematopoiesis, lymphocyte activation, recirculation, and homing, as well as tumor progression and metastasis." (PMID 35164326, 2022). "Furthermore, while erastin alone could induce a modest level of 4-HNE, iron accumulation and strong 4-HNE staining were observed in tumor tissues from the combined treatment group while the MES marker CD44 substantially decreased (upper)." (PMID 35710828, 2022). "We have recently reported the tumor-specific delivery of doxorubicin (Dox) through mExo with hyaluronic acid (HA) decoration, due to HA’s ability to specifically bind to the cluster of differentiation 44 (CD44), which is a well-recognized therapeutic marker overexpressed in specific tumor cells." (PMID 36231028, 2022). "In addition, OC cells overexpressed plasminogen activator inhibitor-1 (PAI-1) and transcription factor DLX4 to induce the expression of IL-8/CXCL5 and IL-1β/CD44 via activating NF-κB signaling, further enhancing tumor-mesothelial cell interactions and facilitating the metastasis." (PMID 36268019, 2022). "Finally, the growth of large, solid tumor microtissues on RGD-free HAGM cryogels, along with HA-mediated CD44 activation, is probably responsible for the overexpression of genetic markers for hypoxia and tumor aggressiveness, including HIF1α, WNT-11, BCL2, CD73, and VEGF." (PMID 35198956, 2022). "However, our studies also demonstrate that the transcription factor Fra-2 is able to control the expression of other adhesion molecules as well (L1-CAM, ICAM-1, CD44, ITGB4, and TSPAN8) and thus allows the tumour cells to adhere to the selectin-deficient endothelium via these adhesion molecules." (PMID 34693476, 2022). "A recent study showed that adipose-derived stromal cells expanded the CD44 v6 positive metastatic colorectal cancer cell compartment, which secreted neurotrophins, nerve growth factor, and neurotrophin-3 to recruit the adipose stem cell population within the tumor mass." (PMID 36550571, 2022). "Consequently, CD44v3 may be a better biomarker in tumor tissue and on tumor sEVs isolated from a liquid biopsy and should be preferred over CD44 in future studies on HNCs." (PMID 35269524, 2022). "Although BCNU wafers may not provide a beneficial effect on the prognosis in highly invasive phenotype of GBM, the treatment may have potential to improve the survival in a low-invasive phenotype of GBM expressing CD44 at a low level in the tumor periphery of GBM." (PMID 35624954, 2022). "In addition, the dietary feeding of FKA-formulated food to Nonobese diabetic/severe combined immunodeficiency (NOD/SCID) mice bearing CD44+/CD133+ 22Rv1 xenograft tumors resulted in a significant reduction of tumor growth compared to those fed with vehicle control food–fed mice." (PMID 35912174, 2022). "Furthermore, it has been shown that CD44+ tumor-infiltrating cells could selectively express PD-L1 to evade immune surveillance compared with CD44− cells." (PMID 36588538, 2022). "Interestingly, the expression of CD44V3, instead of CD44, was greatly increased in tumor tissues." (PMID 36292918, 2022).
tumor (continued). "Thus, HA acts as a potent modulator of tumor microenvironments through its interactions with CD44." (PMID 35456622, 2022). "In addition, the binding of P-selectin to CD44 can eliminate CTCs, preventing tumor metastasis." (PMID 36276645, 2022). "CD44 expression is associated with increased proliferation of the cells, which in turn is due to stimulation of growth pathways (AKT and EGFR), by suppression of tumor suppressor genes, increased resistance to chemotherapy, and invasion of tumor cells to normal healthy cells." (PMID 36185622, 2022). "Moreover, HA binding to CD44 could regulate T cell activation and tumor progression, and the effect of HA fragment in macrophages could be partially inhibited by anti-CD44 antibodies." (PMID 35410993, 2022). "However, it is unknown whether PRG4 inhibits tumor progression by binding to CD44, thereby competing with HA or other ligands." (PMID 35936713, 2022). "The extracellular domain (ETD) of CD44 undergoes binding of hyaluronic acid (HA) and triggers inhibition of cell proliferation, while an interrupted HA binding by ectodomain cleavage or inhibitors has been regarded as an antitumor strategy for high expression of CD44 in many tumor cells." (PMID 35733341, 2022). "However, CD44 isoforms are also present in tumor cells that respond to drugs as well." (PMID 35431911, 2021). "Therefore, HA-decorated nanoparticles could target both tumor cells overexpressing CD44 as well as cancer stem cells." (PMID 34066710, 2021). "Therefore, CD44 has a great significance for HA metabolism and tumor progression, which also provides a theoretical basis for CD44 as a potential therapeutic target in tumor treatment." (PMID 33986244, 2021). "Thus, future studies are necessary to show whether this CD74 and CD44 induction on CTCs could be supportive of an active anti-tumor immune response in the blood flow." (PMID 34209696, 2021). "In addition, it is well known that CD44, the primary membrane receptor of HA, is highly expressed in many tumor cells; thus, the CD44 mediated endocytosis may also contribute to the internalization of HA-es-ZnPP." (PMID 33671291, 2021). "Importantly, we found that SPP1/CD44 interaction plays a critical role in macrophage-mediated activation of MES-like cells by exploring the cell-cell communication among all cellular components in the tumor ecosystem." (PMID 34805184, 2021). "Finally, we asked whether the reduced frequency of IFNγ+CD44+CD8+ TILs in therapy-treated DIO mice was accompanied by increases in the frequencies of myeloid-lineage cells within tumor-bearing kidneys." (PMID 34064933, 2021). "Furthermore, several studies have shown an association between EMT and the acquisition of stem-like properties, such as an elevated tumor-initiating potential, expression of distinct cell surface markers (including CD44 and CD133), and inherent drug resistance." (PMID 33922104, 2021). "To investigate the mechanism underlying the superior abilities of tumour initiation, formation, invasion and metastasis of the ALDH+ CD44+ CXCR4+ CD24+ subpopulation, we performed microarray analysis to identify the DEGs between the ALDH+ CD44+ CXCR4+ CD24+- and ALDH− CD44− CXCR4− CD24−-PCa cells." (PMID 34247196, 2021). "Also, CD44 may serve as a therapeutic target for effectively inhibiting both tumor invasion and proliferation in GBM." (PMID 33543833, 2021). "Indeed, in the in vivo xenograft model, CD24−/low/CD44+ cell-injected mice exhibited greatly increased tumor growth and lung metastasis, accompanied by upregulated expression of EMT-related proteins and increased HIF-1α and ESM-1 levels in tumors and circulating LOX levels in plasma." (PMID 34502547, 2021). "However, it is clear that expression profile of CD44 changes as tumour develops." (PMID 34257584, 2021).
tumor (continued). "The CD44 variant isoforms (CD44v3, CD44v6, CD44v8, etc.), absent in normal tissues, seem to be restricted to aggressive tumors and have crucial roles in the regulation of stemness, self-renewal, tumor initiation, metastasis, and chemoresistance." (PMID 34295890, 2021). "It has been reported that when the tumor progresses after chemotherapy, the CTCs population also changes, with an enrichment in the CTCs of the expression levels of stemness and pluripotency genes such as CD44, ALCAM, EPCAM, NOTCH1, POU5FIB, and PTCH1, or CSC drivers as VEGFB and STAT3." (PMID 33924143, 2021). "Then, Clarke’s group showed that EpCAMhigh/CD44+cells isolated from human CRC could establish a tumor in mice with morphological and phenotypic heterogeneity of the original tumor and concluded that CD44 and EPCAM markers could be considered robust CCSC markers." (PMID 33806312, 2021). "Hence, elevated amounts of circulating Ab could partly saturate binding sites on splenic myeloid cells, thereby allow more 89Zr-anti-CD44 to reach the tumor for accumulation." (PMID 33594192, 2021). "We first examined whether EGFR coordinates with CD44 in tumor clustering." (PMID 33995681, 2021). "Interestingly, the individual BC cells with positive co-staining for both PKD-1 and CD44 were located outside of the tumor nest in patient BC specimens, suggesting that PKD-1 signaling may promote metastatic potential via maintenance of CSC phenotype." (PMID 34168243, 2021). "However, whether the significant impact of Fraction B on glycolytic and glutamine metabolic changes in PDAC tumor is mediated through inhibition of CD44 or through other mechanisms still remains unknown." (PMID 34349642, 2021). "We suggest that following surgical injury, mast cells may play a potential role in that transformation process leading to non-Schwann cell spindle proliferation, a compact collagenous matrix and a CD44 related ability of the tumor to become infiltrative in nature." (PMID 34673814, 2021). "However, CD44-positive mesenchymal tumor stem-like cells may be sensitive to antitumor agents due to their low positive rates for cyclin E and Ki-67." (PMID 34563053, 2021). "A CD44 variant (CD44v), highly expressed in PDAC CSC-like cells, interacts with xCT, a glutamate-cystine transporter, enhances capacity for glutathione (GSH) synthesis to defend against reactive oxygen species (ROS), and thereby maintains CSC and stimulates tumor growth." (PMID 34349642, 2021). "To investigate a possible correlation between CD44 cleavage and stemness in A549 cells, we compared cells cultured in anchorage-dependent monolayer conditions with cells cultured in ultra-low attachment plates, in which tumor cells form spheres enriched in stem-like cancer cells." (PMID 33804427, 2021). "The anti-tumor effect could inhibit the expression of both CD44 and TGF-β." (PMID 34361836, 2021). "Furthermore, 4MU abrogates the proliferation and migration of several tumor cells and some effects of 4MU would be independent of HA synthesis inhibition, such as modulation of metalloproteinases (MMPs) activity and CD44 expression." (PMID 34628469, 2021). "We also highlight CD44 interaction with many components in the tumour microenvironment and its functional roles and involvements in tumour progression and aggressiveness, as well as its clinical relevance and the possibility of targeting CD44 for cancer therapy." (PMID 34944493, 2021). "Finally, the levels of mRNA transcripts of these DEGs among the purified parental CD44+/CD24- CSCs (red color), the newly converted CD44+/CD24- CSCs (blue color) and the unconverted CD44-/CD24- tumor cells (green color) from MDA-MB-231 cells were tested by RT-qPCR." (PMID 34318746, 2021). "Hence, there miR-34a suppresses angiogenesis via directly targeting CD44 in BLCA, and restoration of CD44 could rescue anti-tumor effects of miR-34a." (PMID 33672684, 2021).
tumor (continued). "The binding of HA to CD44 is also known to induce the expression and activity of the large family of matrix metalloproteinases (MMPs), highly homologous, Zn2+-dependent endopeptidases, involved in degradation of extracellular matrix components and tumor progression." (PMID 33958632, 2021). "One of the factors that may have an impact on the acceleration of tumor latency is CD44." (PMID 33540535, 2021). "CD44, a cell surface adhesion receptor for hyaluronic acid (HA), is highly expressed in many cancers and regulates metastasis via recruitment to cell surface; therefore, various HA-based drug delivery systems have been developed for a CD44-mediated tumor targeting." (PMID 33467465, 2021). "Thus, our findings allow the assumption that the resminostat/sorafenib drug combination might reduce the invasive CD44+/CD133+ tumor cell population in HCC." (PMID 33953226, 2021). "HA could also enhance cell-material interactions as it can be recognized by surface antigens, such as CD44, which is highly present in various types of mammalian cells, including normal cells, e.g. hematopoietic cells, epithelial cells or fibroblasts, and tumor cells." (PMID 34073542, 2021). "Additionally, TCGA data demonstrated that CD44 high expression was not linked to tumor grade, T stage, lymph node metastasis, and distal metastasis." (PMID 32434417, 2020). "CD44+ cells, isolated from ascites and solid tumors, are characterized by constitutive nuclear factor-kappa B (NF-κB) activity, cytokine and chemokine production, high capacity of tumor repair and self-renewal, and resistance to conventional chemotherapy, which are unique features of CSCs." (PMID 35582216, 2020). "Similarly, stem-like cells (variously labelled cancer stem cells, tumour-initiating cells) have also been isolated from ccRCC specimens using a variety of different surface markers, including CD44, Ecto-5′-nucleotidase (CD73), CXCR4, CD105 and aldehyde dehydrogenase 1 (ALDH1)." (PMID 32245446, 2020). "Besides, other factors, such as comorbidities of the patients, cancer treatments, and cut-off value to determine the increased tumor CD44 expression may also contribute to the heterogeneity." (PMID 32232385, 2020). "Furthermore, CD44 was shown to target the Wnt/β-catenin signalling pathway in tumour progression." (PMID 33292271, 2020). "Thus, here we isolate by FACS the enriched population of BCSCs (ESA+-CD44+-CD24-/Low cells, from now on CD24-) and the so-called tumor-differentiated cells (ESA+-CD44+-CD24+ cells, from now on CD24+) from MCF7-Tet-On-SrcDN, and test their capacity of self-renewal." (PMID 32673341, 2020). "Notably, nanocomplex-assisted delivery of miRNA-34a induced apoptosis and suppressed migration and proliferation of breast cancer cells as well as reduced tumor growth in a xenograft mouse model via targeting signaling pathways autophagy-related, as CD44 and Notch-1." (PMID 32792960, 2020). "Furthermore, TNBC patient derived xenografts (PDX) grown in the presence of primary adipose stem cells (ASCs) isolated from obese donors (obASCs) had increased HLA1+ human tumor cells and CD44+CD24− CSCs in the peripheral blood and metastasis compared to ASCs from lean women." (PMID 33339340, 2020). "Since we previously observed a strong effect of holo-LCN-2 on tumour cell migration, we then performed qRT-PCR analysis of migration-associated genes, such as the transcription factor Snail, the epithelial marker CDH1, the mesenchymal marker fibronectin as well as the stemness markers CD24 and CD44." (PMID 31772326, 2020). "These polymer-based strategies of miRNA-34a delivery might represent novel therapeutic challenges with highly selective tumor cell death and tumor growth inhibition in CD44-positive tumors, thus opening a therapeutic window for autophagy inhibition for cancer treatment." (PMID 32792960, 2020).